ZNF90 (zinc finger protein 90)
Description:
May be involved in transcriptional regulation.
Synonyms: HTF9
Tractability: PROTAC: ubiquitination databases record sites on it.
Gene: Protein-coding gene on chromosome 19 (20,077,994 to 20,127,076, forward strand). Ensembl gene ENSG00000213988.
Subcellular location: Nucleus
Subcellular location (Human Protein Atlas): Nucleoplasm; Golgi apparatus
Gene Ontology:
Molecular function: DNA-binding transcription factor activity; DNA-binding transcription factor activity, RNA polymerase II-specific; RNA polymerase II cis-regulatory region sequence-specific DNA binding; zinc ion binding
Biological process: regulation of DNA-templated transcription; regulation of transcription by RNA polymerase II
Cellular component: nucleus
Genetic constraint (gnomAD): Loss-of-function variants: 8 observed, 11.19 expected, observed/expected ratio (o/e) 0.71, 90% interval 0.42 to 1.29. The upper end of that interval is the gene's LOEUF score, 1.29, which puts it in group 5 of 6, group 1 being the genes least tolerant of losing a copy. Missense variants: 765 observed, 708.49 expected, observed/expected ratio (o/e) 1.08, 90% interval 1.02 to 1.15. Synonymous variants: 232 observed, 241.06 expected, observed/expected ratio (o/e) 0.96, 90% interval 0.86 to 1.07.
Homologues: Orthologues: chimpanzee ZNF90 (99% identical). Paralogues in human: ZNF726 (66% identical), ZNF728 (66% identical), ZNF254 (66% identical), ZNF708 (65% identical), ZNF676 (61% identical), ZNF85 (60% identical), ZNF724 (59% identical), ZNF93 (59% identical), ZNF493 (58% identical), ZNF43 (57% identical), ZNF492 (57% identical), ZNF429 (55% identical), and 164 more.
Diseases named in the same sentence as ZNF90 in open-access papers:
ZNF90 is named in the same sentence as 7 diseases in open-access papers, as found by Europe PMC text mining. Sharing a sentence is not in itself a finding about the gene and the disease. The quoted sentences say what the papers report.
COVID-19 (1 paper, 2022). A disease caused by infection with severe acute respiratory syndrome coronavirus 2. "GFI1, ZNF90, E2F8, E2F2, and EZH2 were also specific to exhausted T cells and may play a vital role in TEX in severe COVID-19." (PMID 35694714, 2022).
HIV-1 infection (1 paper, 2022). The type species of lentivirus and the etiologic agent of acquired immunodeficiency syndrome (AIDS). "The top downregulated transcripts in cells from treated individuals were the transcription factor ZNF90; NHSL2, which has unknown function; and IL7R, which has been shown to play a role in CD4 T cell loss during HIV-1 infection." (PMID 36175869, 2022). "We observed a similar downregulation of ZNF90 and IL7R when we compared ART to seronegative cells as when we compared untreated HIV cells were compared to seronegative, indicating these transcripts are changed in T cells during untreated or treated HIV-1 infection." (PMID 36175869, 2022).
vitiligo (1 paper, 2024). Generalized well circumscribed patches of leukoderma that are generally distributed over symmetric body locations and is due to autoimmune destruction of melanocytes. "Autologous serum- and feeder-free cultured epithelium showcases comparable efficacy, increased safety over serum- and feeder-dependent epithelium, revealing the role of LAMB3+ keratinocytes and ZNF90+ fibroblasts in vitiligo." (PMID 38200141, 2024). "Thus, it could be hypothesized that FN1 is an essential molecular marker for ZNF90+ fibroblasts, which facilitates repigmentation when transplanting cultured epithelial sheets onto patients with vitiligo." (PMID 38200141, 2024). "From bench to bedside and back again, we found that, in the absence of serum and feeder, LAMB3+ basal keratinocytes and ZNF90+ fibroblasts may promote repigmentation in cultured autologous epithelial sheets in the treatment of patients with refractory vitiligo." (PMID 38200141, 2024).
ZNF90 also shares sentences with these, for which no sentence is quoted: gastric cancer (1 paper); glioma (1); ovarian carcinoma (1); tumor (1).